ABCC8 (ATP binding cassette subfamily C member 8)
Diseases named in the same sentence as ABCC8 in open-access papers (continued):
Sharing a sentence is not in itself a finding about the gene and the disease.
diabetes (continued). "What emerges from the available data is that not only ABCC8-related diabetes can result from both activating and inactivating mutations, but variants located in the same protein domain – or even in the same mutation site – can give different phenotypes throughout the disease spectrum." (PMID 38980630, 2024). "The ABCC8-associated phenotype may depend on the type of mutation: variants activating the channel cause diabetes mellitus, whereas inactivating ones usually induce hyperinsulinism." (PMID 36836406, 2023). "This could also be a coincidence, and the ABCC8 mutation might play a leading role in the occurrence of diabetes." (PMID 35992135, 2022). "Diabetes is a common metabolic comorbidity associated with adult-onset PAH; whether heterozygous variants in ABCC8 contribute to the co-occurrence of diabetes and adult-onset PAH remains an open question." (PMID 35204766, 2022). "Although dyslipidaemia, hypertension, and possible genetic factors contribute to the early manifestation of diabetes complications, the ABCC8 variants may be responsible for the rapid progression to proliferative retinopathy." (PMID 34631896, 2021). "In contrast, activating mutations in ABCC8 have been described in diabetes." (PMID 34079523, 2021). "Previous studies reported that both gain-of-function and loss-of-function variants in ABCC8 could cause diabetes." (PMID 34631896, 2021). "In addition, two Japanese patients with hypoglycemia in infancy progressed to diabetes later in life due to the ABCC8 heterozygous inactivating variants and got better glucose control treated with DPP4 inhibitors." (PMID 34631896, 2021). "In addition, the development in the field of ABCC8 gene-related diabetes has included de novo variants identified by new rapid molecular genetic features, symptoms, and medical therapy (sulfonylureas, DPP4-inhibitor)." (PMID 34631896, 2021). "In addition, an East Asian study found one (0.9%) ABCC8 variant among 109 suspected monogenic diabetes patients." (PMID 34631896, 2021). "Mutations in the ABCC8 gene are closely related to diabetes." (PMID 32337264, 2020). "Since our study had excluded patients with a personal or a family history of NDM, it confirmed that ABCC8/KCNJ11 variants can cause a milder form of diabetes that may reveal as adult-onset diabetes." (PMID 31291970, 2019). "Patients with homozygous ABCC8 mutations who are managed medically should be followed long-term as they may be at increased risk of developing diabetes after many years." (PMID 29739729, 2019). "Our detailed genetic and familial study revealed that this disease association was rather explained by independent mutations in two genes that were known to cause diabetes (ABCC8) and congenital cataract (CRYBB1), respectively dominant and recessive, both of which with incomplete penetrance." (PMID 29112131, 2017). "The aim of this study was to investigate how a homozygous nonsense mutation in ABCC8 could result in neonatal diabetes." (PMID 28663158, 2017). "The clinical presentation of the patient shares features of T1D (juvenile onset diabetes with acute onset and continuous insulin-treatment) and of ABCC8-mutated diabetes, including good control with relatively low insulin doses and no history of associated autoimmune disorders." (PMID 29112131, 2017). "The family study showed that both the mother and one sister, who were not known to be diabetic at the time of the study at ages 47 years and 23 years respectively, were heterozygous for the same ABCC8 mutation as the affected child who had diabetes at the age of 6 years old." (PMID 29112131, 2017). "STZ treatment also suppressed expression of a wide range of genes linked with key β-cell functions or diabetes development, such as G6pc2, Slc2a2 (Glut2), Slc30a8, Neurod1, Ucn3, Gad1, Isl1, Foxa2, Vdr, Pdx1, Fkbp1b and Abcc8, suggesting global β-cell defects in STZ-treated islets." (PMID 23828045, 2013).
diabetes (continued). "However, the identification of genetic causes, in particular, the two main mutations that cause PNDM (KCNJ11 and ABCC8), has led to the development of effective treatment options for many children with this type of diabetes, particularly those with KCNJ11 mutations." (PMID 39457190, 2024). "Therefore, the subtype of ABCC8-NNDM due to inactivating variants could implicate the etiology of diabetes." (PMID 34631896, 2021). "Therefore, variants in ABCC8 gene could cause variable phenotypes: diabetes and HH, due to the different effects of the variants on channel function." (PMID 34631896, 2021). "Studies in animal models indicate that activating ABCC8 variants may lead to diabetes, and since 2006, multiple studies have linked it to a wide range of clinical types of diabetes, including transient neonatal diabetes mellitus, and permanent neonatal diabetes mellitus." (PMID 35002955, 2021). "In addition, 21 (24%) probands with dominant loss-of-function variants in ABCC8 previously reported could cause hyperinsulinism in the early period and progress to diabetes later." (PMID 34631896, 2021). "Isolated Diabetes: Primarily caused by defects in the functional machinery of the β-cell (e.g., KCNJ11, ABCC8, INS)." (PMID 41614934, 2026). "While diabetes arising from ABCC8 and KCNJ11 requires high-dose sulfonylureas, a low-dose sulfonylureas is sufficient to obtain good control of blood glucose levels in the majority of HNF4A-MODY and HNF1A-MODY patients." (PMID 39504571, 2025). "Variants in the genes GCK, HNF1A, HNF1B, HNF4A, ABCC8, INS, and INSR were the main contributors to the genetic pathogenesis of hereditary diabetes mellitus in the Russian cohort." (PMID 39859454, 2025). "Reports from India have described an even broader mutation spectrum, including ABCC8, HNF1B, and INS variants, collectively accounting for a substantial proportion of monogenic diabetes diagnoses." (PMID 41367630, 2025). "We run the search on PubMed and specific search terms were: “Maturity-Onset Diabetes of the Young (MODY)”, “ABCC8-MODY”, “MODY12”, “ABCC8 variants”." (PMID 38980630, 2024). "Three ABCC8 variants (p.G1478R, p.L580_S581insFASL, and p.S986⁣∗) and two HNF4A variants (p.R63W and p.V382I) were previously reported to be associated with diabetes." (PMID 40302972, 2024). "A recent study of the diabetes prospective follow‐up (DPV) initiative analyzed individuals with ABCC8‐MODY or KCNJ11‐MODY and reported a switch from insulin to oral sulfonylureas in most persons while maintaining good metabolic control." (PMID 39511990, 2024). "Variants in the potassium channel (ABCC8 or KCNJ11) are often associated with neonatal diabetes, but the onset of diabetes can also occur later in life." (PMID 39511990, 2024). "“Tier 2” additionally includes four genes within the top 50 genes and either being causal for monogenic diabetes or harboring causal coding variants of T2D35 (GCK, SLC30A8, ABCC8, and PAM)." (PMID 37292813, 2023). "The “monogenic diabetes” gene group contains HNF1A, GCK, RFX6, and ABCC8, which harbor variants that cause MODY." (PMID 37292813, 2023). "Comparison of clinical characteristics of children with diabetes caused by a mutation in INS, KCNJ11, or ABCC8." (PMID 35518939, 2022). "The benign trajectory of diabetes due to pathogenic GCK mutations, and the sulfonylurea-hyperresponsiveness conferred by activating KCNJ11 or ABCC8 mutations, or loss-of-function HNF1A or HNF4A mutations, often decisively guide clinical management." (PMID 35618782, 2022). "ABCA1/ABCA7 is bound up with Alzheimer’s disease, ABCA4 is in connection with Stargardt macular degeneration, and ABCC8/SUR1 and ABCC9/SUR2 are both associated with diabetes." (PMID 35783291, 2022). "The variants found in the ABCC8 and KCNJ11 genes have been published in cases with neonatal diabetes phenotype." (PMID 34440499, 2021).
diabetes (continued). "Elsewhere, the Arg521Gln substitution in the ABCC8 protein has been identified in a female with dominant hyperinsulinism and in a case of a heterozygous carrier with diabetes." (PMID 33477506, 2021). "It is essential to perform rapid genetic testing for ABCC8/KCNJ11 in any patient diagnosed with diabetes before 6 months of age, particularly given issues regarding access to and cost of insulin in some populations." (PMID 34566892, 2021). "Next generation sequencing (NGS) enables a rapid and cost-effective diagnosis, and it should be taken into consideration for the ABCC8 gene in early onset diabetes." (PMID 34631896, 2021). "If a diagnosis of diabetes is made before 6 months of age and genetic screening is undertaken, the identification of mutations in KCNJ11 or ABCC8 provides an alternative therapeutic strategy." (PMID 34566892, 2021). "Variants in the genes encoding Kir6.2 and SUR1, KCNJ11 and ABCC8, are commonly associated with insulin secretion disorders and diabetes and many of these variants cause trafficking defects of KATP channels." (PMID 31934859, 2020). "In our research, several genes, such as ABCC8 and KCNJ11, related to insulin and diabetes and encoding Kir6.2 and SUR1 have also been found in the ceRNA network." (PMID 32906679, 2020). "Candidate target genes also included six genes involved in MODY and other monogenic and syndromic forms of diabetes (ABCC8, KCNJ11, GCK, INS, GLIS3, WFS1)." (PMID 31064983, 2019). "Hyperinsulinaemic hypoglycaemia in infancy and diabetes in later life have been reported in patients with HNF1A, HNF4A and ABCC8 mutations." (PMID 29739729, 2019). "The PCS also highlighted several other highly scoring candidates with known causal roles in relation to diabetes and obesity such as MC4R (PCS = 0.43), WFS1 (0.41), ABCC8 (0.37), LEP (0.27), GCK (0.24) and HNF1A (0.23)." (PMID 30914061, 2019). "Gain-of-function ABCC8 and KCNJ11 gene mutations have been reported to cause rare forms of MODY (ABCC8-MODY 12 and KCNJ11-MODY13) with variable clinical presentation, ranging from asymptomatic glucose intolerance to overt diabetes, with age." (PMID 31137773, 2019). "Herein, we present a patient with a novel, homozygous ABCC8 mutation who was diagnosed with CHI in the neonatal period and developed diabetes at the age of nine years." (PMID 29739729, 2019). "Among individuals with young onset and adult onset diabetes, 40 individuals (1.8% of subjects with early onset diabetes and 0.6% with late onset) were carriers of known pathogenic missense mutations in the GCK, HNF1A, HNF4A, HNF1B, ABCC8, and INS genes." (PMID 29207974, 2017). "A total of 40 individuals with diabetes (1.8% of early onset sub-group and 0.6% of adult onset sub-group) were carriers of known pathogenic missense variants in the GCK, HNF1A, HNF4A, ABCC8, and INS genes." (PMID 29207974, 2017). "Although a diagnosis of diabetes before 6 months of life is highly suggestive of a genetic cause, in such cases other types of monogenic diabetes (due to mutations in KCNJ11, INS or ABCC8 genes) are more plausible and should be evaluated before MODY2." (PMID 24244580, 2013). "Beyond neonatal diabetes mellitus (NDM), KCNJ11 is also a MODY gene (‘MODY13’), confirming the wide spectrum of diabetes related phenotypes due to mutations in NDM genes (i.e. KCNJ11, ABCC8 and INS)." (PMID 22701567, 2012). "Monogenic form of diabetes by ABCC8 gene mutations: Activating heterozygous mutations in KCNJ11 and ABCC8 genes, which form the ATP-sensitive K+ channel, usually causes transient or permanent neonatal diabetes." (PMID 22284844, 2012). "Some of the genes associated with both monogenic (ABCC8 and KCNJ11) and complex diabetes (KCNJ11, KCNQ1) encode subunits of these potassium channels and accordingly, monogenic diabetes of this type can be well managed with sulfonylureas." (PMID 19794883, 2009).
diabetes (continued). "In our study, we are the first to reveal that targeting KCNJ11/ABCC8 for diabetes treatment could reduce the incidence of PT from a genetic perspective, with gene expression analysis further supporting the role of KCNJ11 in PT." (PMID 41357784, 2025). "Interestingly, ATP-binding cassettes KCNJ and ABCC8 involved in neonatal and maturity onset of diabetes and PD have been observed to be downregulated on treatment with WS deciphering the neuroprotective and antidiabetic role of WS in SK-N-SH cells." (PMID 40636521, 2025). "Finally, activating ABCC8 mutations have been shown to cause ABCC8-MODY, characterized by variable clinical phenotypes of diabetes with an onset in childhood/early adulthood." (PMID 38980630, 2024). "In a recent study of 18 nonpancreatectomized patients with ABCC8 variants, 41.7% of patients subsequently progressed to diabetes." (PMID 38212772, 2024). "Our result is in accordance with another study showing the wide spectrum of clinical forms of ABCC8 mutations, ranging from permanent neonatal diabetes mellitus (PNDM) to less severe forms of diabetes with variable expression and age at onset (M. Li, Han, and Ji, 2021)." (PMID 38162681, 2023). "Importantly, sQTLs also affected genes that harbor variants that cause monogenic diabetes (KCNK16, ABCC8, PDX1) or influence T2D risk (THADA, PAM) as well as genes that play a role in T1D pathogenesis (ICA1, PTPRN2, HLA-B)." (PMID 36109769, 2022). "Both KCNJ11 and ABCC8 genes are useful in diagnosing monogenic diabetes during infancy." (PMID 34584998, 2021). "Prominent examples are well-known diabetes genes such as Tcf7l2 and Abcc8 (also named Sur1)." (PMID 34445304, 2021). "Earlier studies regarding transcriptional regulation of Abcc8 were performed in models of diabetes." (PMID 34769328, 2021). "Patients with homozygous ABCC8 mutations can present with CHI in the newborn period, the hyperinsulinism can show variability in terms of clinical severity and age at presentation and can cause diabetes later in life." (PMID 29739729, 2019). "To date, there were no reports on NEUROD1, INS, BLK and ABCC8 variants in pregnant women with diabetes." (PMID 28095440, 2017). "However, they are related to diabetes or insulin secretion (rs757110 in ABCC8, rs5215 and rs5219 in KCNJ11), carotid intima media thickness (rs2468844 in SAA2), and oligospermia (rs11703684 in PIWIL3)." (PMID 27900359, 2016). "The patient with no identifiable mutations and diffuse pancreatic disease and the patient with a paternally inherited ABCC8 mutation and a focal lesion have not yet developed diabetes." (PMID 26758964, 2016). "Parents who carried the same KCNJ11 or ABCC8 mutations showed no neonatal diabetes mellitus symptoms or past history of abnormal glucose metabolism." (PMID 26839896, 2016). "Inactivating or activating mutations in one of the two subunits forming this channel, i.e., the sulfonylurea receptor-1 gene (SUR1, ABCC8) or the inward rectifier K+ channel (Kir6.2, KCNJ11), cause congenital hyperinsulinemic hypoglycemia and diabetes in neonates and infants." (PMID 26400961, 2015). "We use FHS 100K SNPs in an in silico replication analysis that tests the hypothesis that SNPs in LD with published causal variants in PPARG, ABCC8, TCF7L2, CAPN10, and HNFa are associated with diabetes and related quantitative traits." (PMID 17903298, 2007). "One 100K SNP (rs878208) ~25 kb upstream of ABCC8 showed nominal association with risk of diabetes, but it was not in LD with rs757110 in ABCC8 (r2 = 0.04)." (PMID 17903298, 2007). "Heterozygous mutations in the ABCC8 gene have been well-documented in leucine-sensitive neonatal hypoglycemia (OMIM:240800), transient neonatal diabetes mellitus 2 (OMIM:610374), and non-insulin-dependent diabetes mellitus (OMIM:125853), all exhibiting autosomal-dominant inheritance." (PMID 39859454, 2025).
diabetes (continued). "However, predicting a phenotype based solely on the functional effect of the ABCC8 variant can be misleading, since there are reports of diabetes owing to LOF mutations in ABCC8 in the absence of the hyperinsulinism-remission-diabetes sequence." (PMID 38980630, 2024). "ABCC8/KCNJ11 gain-of-function (GOF) mutations cause the permanent opening of the KATP channel, and thus reduce insulin secretion and eventually cause hyperglycemia with a wide spectrum of diabetes phenotypes, ranging from neonatal diabetes to MODY to adult-onset diabetes." (PMID 35052457, 2022). "Additionally, ABCC8 was thought to be involved in the development of diabetes." (PMID 36408280, 2022). "However, because the variant (c.1432G>A) in the ABCC8 gene has not been previously reported, functional studies are needed to uncover the underlying mechanism and confirm the role of the variant in diabetes of this family." (PMID 35002955, 2021). "Activating variants in the ABCC8 gene led to an increased probability of opening of the potassium channel, therefore preventing any activation of the voltage-dependent calcium channel and any glucose-induced insulin secretion, leading to NDM, early onset diabetes, and MODY." (PMID 34631896, 2021). "CHI within the neonatal period and evolution to diabetes later in life has been reported in individuals with heterozygous inactivating mutations in the hepatocyte nuclear factor 4A and 1A genes (HNF4A and HNF1A) and dominant mutations in ABCC8 genes in a very limited number of cases." (PMID 29739729, 2019). "We, therefore, were not able to confirm whether the diabetes in these additional family members was due to the ABCC8 mutation." (PMID 29739729, 2019). "The Kir6.2 protein along with another protein SUR1 encoded by the ABCC8 gene located next to the KCNJ11 gene forms the KATP channel which modulates insulin production and secretion through glucose metabolism and is the target of sulphonylurea drugs used for treating diabetes." (PMID 28330327, 2016). "Finally, the example of single gene diabetes, particularly HNF1A MODY and permanent neonatal diabetes associated with the KCNJ11 and ABCC8 genes, all efficiently controlled on sulfonylurea, inspires us to continue the efforts to tailor individual treatment for T2DM patients." (PMID 22996131, 2012). "Since overnutrition is common in pre-diabetes, we compared transcriptomes of FACS-purified β-cells of Abcc8 knockout mice, which serve as a model for excitotoxicity, with mice fed a HFD." (PMID 39015185, 2024). "Thus, in the absence of other possible causes of diabetes, it seems reasonable to hypothesize a role of the identified ABCC8 gene variants in such insulin secretory dysfunction." (PMID 38980630, 2024). "The ABCC8-R1393H mutation may not be the only cause of diabetes, since the father of the proband carrying this mutation only showed glucose intolerance, whereas the proband’s mother without the mutation was diagnosed with diabetes at 33 years of age." (PMID 39556225, 2024). "In both T1D and T2D, we found enrichment of monogenic forms of diabetes, as expected —2 genes in T1D (RASGRP1, INS) and 8 in T2D (HNF1B, GCK, WFS1, KCNJ11, ABCC8, HNF1A, PPARG, SLC2A2)." (PMID 33836063, 2021). "ABCC8, a member of the MRP family involved in multidrug resistance, has a role in diabetes and recently expression patterns of the ABC family were suggested to be new hallmarks of cancer." (PMID 34797887, 2021). "Patients with dominant mutations of KATP channel genes, ABCC8 and KCNJ11, may cause variable phenotype ranging from asymptomatic macrosomia, mild diazoxide responsive CHI to severe persistent hyperinsulinaemic hypoglycaemia (HH) as well as diabetes mellitus in later life." (PMID 29739729, 2019). "The number of variants detected was greater than in Stage 1 since five additional monogenic diabetes genes (CEL, EIF2AK3, ABCC8, BLK, and KLF11) were sequenced." (PMID 29207974, 2017).